APOOL (apolipoprotein O like)
Description:
Component of the MICOS complex, a large protein complex of the mitochondrial inner membrane that plays crucial roles in the maintenance of crista junctions, inner membrane architecture, and formation of contact sites to the outer membrane. Specifically binds to cardiolipin (in vitro) but not to the precursor lipid phosphatidylglycerol. Plays a crucial role in crista junction formation and mitochondrial function,.
Synonyms: CXorf33; FAM121A; MIC27; UNQ8193; AAIR8193; MICOS27
Tractability: Antibody: its Gene Ontology location is reachable by antibodies, with high confidence; UniProt predicts a signal peptide or a membrane-spanning region. PROTAC: ubiquitination databases record sites on it; its protein half-life has been measured.
Gene: Protein-coding gene on chromosome X (85,003,871 to 85,093,315, forward strand). Ensembl gene ENSG00000155008.
Subcellular location: Mitochondrion inner membrane; Mitochondrion
Subcellular location (Human Protein Atlas): Mitochondria
Pathways (Reactome):
Hemostasis: Platelet degranulation
Organelle biogenesis and maintenance: Cristae formation
Gene Ontology:
Molecular function: protein binding
Biological process: cristae formation; inner mitochondrial membrane organization
Cellular component: MIB complex; MICOS complex; mitochondrial inner membrane; mitochondrion; SAM complex; extracellular region; mitochondrial crista junction; platelet alpha granule lumen
Homologues: Orthologues: chimpanzee APOOL (99% identical), macaque APOOL (87% identical), dog APOOL (85% identical), mouse Apool (77% identical), guinea pig APOOL (75% identical), pig APOOL (74% identical), rabbit APOOL (73% identical), rat Apool (73% identical), zebrafish apool (36% identical), Drosophila melanogaster Mic26-27 (22% identical), Caenorhabditis elegans moma-1 (20% identical). Paralogues in human: APOO (25% identical).
Diseases named in the same sentence as APOOL in open-access papers:
APOOL is named in the same sentence as 9 diseases in open-access papers, as found by Europe PMC text mining. Sharing a sentence is not in itself a finding about the gene and the disease. The quoted sentences say what the papers report.
tumor (3 papers, 2023 to 2024). "APOOL and HINT3 are tumor-related genes that were first discovered in this study as new prognostic markers for BC, but the mechanism of these genes in BC remains to be clarified." (PMID 38245717, 2024). "In the TCGA datasets, BC tumor tissue showed elevated gene expression levels of IMMT, CHCHD6, CHCHD3, APOO, and MICOS10 as compared to normal tissue, while the APOOL level was decreased in tumor tissue as compared to normal tissue." (PMID 36899366, 2023). "Specifically, expression levels of BCL2, SLC40A1, and TFF1 were decreased in BCa samples with respect to normal tissues, whereas APOOL and PRAME were increased in tumor samples." (PMID 37728703, 2023).
APOOL also shares sentences with these, for which no sentence is quoted: diabetic cardiomyopathy (1 paper); esophageal carcinoma (1); glioblastoma (1); Hyperglycemia (1); hyperthyroidism (1); infection (1); Listeria infection (1); Mitochondrial myopathy (1).